H2AC21 (H2A clustered histone 21)
Description:
Core component of nucleosome. Nucleosomes wrap and compact DNA into chromatin, limiting DNA accessibility to the cellular machineries which require DNA as a template. Histones thereby play a central role in transcription regulation, DNA repair, DNA replication and chromosomal stability. DNA accessibility is regulated via a complex set of post-translational modifications of histones, also called histone code, and nucleosome remodeling.
Synonyms: HIST2H2AB; H2AB
Tractability: PROTAC: UniProt records ubiquitination sites on it; ubiquitination databases record sites on it.
Gene: Protein-coding gene on chromosome 1 (149,887,469 to 149,887,965, reverse strand). Ensembl gene ENSG00000184270.
Subcellular location: Nucleus; Chromosome
Subcellular location (Human Protein Atlas): Nucleoplasm
Pathways (Reactome):
Chromatin organization: HATs acetylate histones; HDACs deacetylate histones; RMTs methylate histone arginines
Disease: Dengue Virus-Host Interactions; HCMV Early Events; HCMV Late Events
Metabolism of proteins: Metalloprotease DUBs; UCH proteinases; Ub-specific processing proteases
Gene Ontology:
Molecular function: protein binding; structural constituent of chromatin; DNA binding; protein heterodimerization activity
Biological process: heterochromatin formation
Cellular component: extracellular exosome; nucleoplasm; nucleus; nucleosome; chromosome
Genetic constraint (gnomAD): Loss-of-function variants: 3 observed, 8.28 expected, observed/expected ratio (o/e) 0.36, 90% interval 0.16 to 0.94. That is too few expected variants to judge how well the gene tolerates losing a copy. Missense variants: 173 observed, 191.68 expected, observed/expected ratio (o/e) 0.9, 90% interval 0.8 to 1.02. Synonymous variants: 119 observed, 87.89 expected, observed/expected ratio (o/e) 1.35, 90% interval 1.17 to 1.58.
Homologues: Orthologues: chimpanzee H2AC21 (100% identical), dog H2AC21 (100% identical), guinea pig H2AC21 (100% identical), macaque H2AC21 (100% identical), pig H2AC21 (100% identical), mouse H2ac21 (99% identical), tropical clawed frog h2ac12 (95% identical), tropical clawed frog h2ac14 (95% identical), tropical clawed frog h2ac21 (95% identical), zebrafish h2af1al (72% identical), Caenorhabditis elegans htas-1 (48% identical). Paralogues in human: H2AC6 (95% identical), H2AC11 (95% identical), H2AC13 (95% identical), H2AC15 (95% identical), H2AC16 (95% identical), H2AC17 (95% identical), H2AC18 (95% identical), H2AC19 (95% identical), H2AC20 (95% identical), H2AC25 (95% identical), H2AC12 (94% identical), H2AC14 (94% identical), and 15 more.
Diseases named in the same sentence as H2AC21 in open-access papers:
H2AC21 is named in the same sentence as 4 diseases in open-access papers, as found by Europe PMC text mining. Sharing a sentence is not in itself a finding about the gene and the disease. The quoted sentences say what the papers report.
tumor (1 paper, 2022). "However, the roles of H2AC12 and H2AC21 genes in tumors have not been explored so far; therefore, the mechanisms of these genes in tumor development can be further investigated in the future." (PMID 36553511, 2022).
H2AC21 also shares sentences with these, for which no sentence is quoted: cancer (1 paper); Sepsis (1); systemic lupus erythematosus (1).